SYT15 (synaptotagmin 15)
Description:
May be involved in the trafficking and exocytosis of secretory vesicles in non-neuronal tissues.
Synonyms: SytXV; CHR10SYT
Tractability: Antibody: UniProt places it where antibodies can reach, with medium confidence; UniProt predicts a signal peptide or a membrane-spanning region; its Gene Ontology location is reachable by antibodies, with medium confidence.
Gene: Protein-coding gene on chromosome 10 (46,578,217 to 46,594,173, forward strand). Ensembl gene ENSG00000204176.
Subcellular location: Cell membrane (Isoform 1); Cell membrane (Isoform 2); Cell membrane (Isoform 4)
Subcellular location (Human Protein Atlas): Golgi apparatus
Gene Ontology:
Molecular function: calcium ion sensor activity; calcium-dependent phospholipid binding; SNARE binding
Biological process: regulation of calcium ion-dependent exocytosis; vesicle-mediated transport
Cellular component: exocytic vesicle; plasma membrane
Genetic constraint (gnomAD): Loss-of-function variants: 2 observed, 10.1 expected, observed/expected ratio (o/e) 0.2, 90% interval 0.08 to 0.62. The synonymous counts are far from expectation, so gnomAD's model fits this gene poorly and the ratio says little. Missense variants: 29 observed, 126.09 expected, observed/expected ratio (o/e) 0.23, 90% interval 0.17 to 0.31. Synonymous variants: 7 observed, 43.63 expected, observed/expected ratio (o/e) 0.16, 90% interval 0.09 to 0.3.
Homologues: Orthologues: macaque SYT15 (96% identical), mouse Syt15 (78% identical), rat Syt15 (77% identical), tropical clawed frog syt15 (60% identical), zebrafish syt15 (38% identical). Paralogues in human: SYT15B (100% identical), SYT17 (28% identical), SYT3 (28% identical), SYT9 (28% identical), SYT6 (27% identical), SYT10 (27% identical), SYT5 (26% identical), SYT1 (25% identical), SYT2 (25% identical), SYTL4 (25% identical), SYT14 (24% identical), SYT4 (24% identical), and 19 more.
Diseases named in the same sentence as SYT15 in open-access papers:
SYT15 is named in the same sentence as 2 diseases in open-access papers, as found by Europe PMC text mining. Sharing a sentence is not in itself a finding about the gene and the disease. The quoted sentences say what the papers report.
cervical cancer (1 paper, 2021). A primary or metastatic malignant neoplasm involving the cervix. "As for circ_0018289, generated from the exons of synaptotagmin 15 (SYT15) mRNA, it was demonstrated to be upregulated in cervical cancer, highlighting its potential as a promising biomarker for the outcome of patients." (PMID 34404391, 2021).
Hydrocephalus (1 paper, 2012). Hydrocephalus is an active distension of the ventricular system of the brain resulting from inadequate passage of CSF from its point of production within the cerebral ventricles to its point of absorption into the systemic circulation. "An additional sample with two events was a fetus with hydrocephalus found to have two duplication CNVs, on chromosome bands 1p33 (including the genes FAAH, DMBX1 and KNCN) and 10q11.22 (containing the genes SYT15, GPRIN2 and PPYR1), but parental samples were not available in this case." (PMID 23056206, 2012).